NF2 (NF2, moesin-ezrin-radixin like (MERLIN) tumor suppressor)
Diseases named in the same sentence as NF2 in open-access papers (continued):
Sharing a sentence is not in itself a finding about the gene and the disease.
schwannoma (continued). "In NF2 patients, the number of Foxp3-positive cells in schwannomas with a progressive course was significantly higher than in those without a progressive course, suggesting that growth may be associated with Foxp3-positive regulatory T cells (Tregs)." (PMID 31848332, 2019). "Germline mutations within LZTR1 or NF2 were neither detected in blood‐derived DNA of patient II.4 nor in genomic DNA isolated from schwannoma T2763 of patient II." (PMID 29779243, 2018). "Given that recent data, we questioned whether COX-2 inhibition could be used as a chemopreventative strategy in NF2 mediated schwannoma formation, especially in light of the success of inhibition of COX-2 in other cancer predisposition syndromes." (PMID 29416648, 2018). "Interestingly, the treatment of NF2-null Schwann or schwannoma cells with a COX-2 inhibitor, celecoxib, dramatically inhibited cell growth in vitro and in vivo, which suggests that COX-2 is a potential therapeutic target in NF2-null tumors." (PMID 29587439, 2018). "There are currently no approved chemotherapeutic agents for the treatment of schwannomas, owing in part to an incomplete understanding of the biochemical derangements that occur as a result of NF2-deficiency." (PMID 29416648, 2018). "The mutant NF2 transcripts are usually underexpressed or inefficiently translated in schwannomas." (PMID 28710469, 2017). "By contrast, in patients with sporadically occurring schwannomas and in patients with schwannomatosis, the somatic NF2 mutations occur rather later during development and neither group of patients exhibits BVS." (PMID 27921248, 2017). "In eight of these ten schwannomas, 22q LOH was detected, but an intragenic NF2 gene mutation could not be found, whereas two of ten schwannomas harboured an intragenic NF2 mutation, while heterozygosity of 22q markers was retained." (PMID 27921248, 2017). "Drugs that simply slow schwannoma growth would benefit NF2 patients enormously." (PMID 28427224, 2017). "Ponatinib therapy may be applicable to a larger patient population than NF2, considering that merlin inactivation also occurs in sporadic schwannomas." (PMID 28427224, 2017). "A combination of linkage analysis in affected families and mutation screening of the NF2 gene in schwannomas indicated that schwannomatosis is not due to germline mutations in the NF2 gene." (PMID 27921248, 2017). "Furthermore, immunohistochemical staining indicated normal protein expression levels of SMARCB1, LZTR1, and NF2 in both schwannomas." (PMID 27921248, 2017). "Although biallelic mutations of SMARCB1 or LZTR1 have been detected in the tumours of patients with schwannomatosis, the classical two-hit model of tumorigenesis is insufficient to account for schwannoma growth, since NF2 is also frequently inactivated in these tumours." (PMID 27921248, 2017). "The affected family members did not appear to harbour germline mutations in SMARCB1, LZTR1, or NF2; nor were somatic mutations of these genes detected in two schwannomas from two family members." (PMID 27921248, 2017). "Although the ABPP identified at least ten potential candidates for crizotinib's activity, given the previous reports correlating NF2 deficiency to sensitivity of FAK1 inhibition we focused initially on FAK1 as the potential relevant crizotinib target in NF2-null schwannoma cells." (PMID 27363027, 2016). "However, the identification of diversified signaling events related to the merlin tumor suppressor protein has yet to lead to the development of better therapeutic options for the management of sporadic or NF2-related schwannomas." (PMID 27236462, 2016). "Tumor formation from Schwann cells into schwannomas is mainly thought to be dependent on bi-allelic inactivation of the Nf2 tumor suppressor gene, in line with Knudson’s two-hit hypothesis." (PMID 27236462, 2016). "However, loss of heterozygosity (LOH) has reportedly been detected in only 67 % of NF2-related and 56/57 % of sporadic schwannomas." (PMID 27236462, 2016).
schwannoma (continued). "Ultimately, macrophage occurrence indicated by both CD68 and Iba-1 expression was also found in 28 out of 30 human biopsy samples from sporadic schwannomas, 9 out of 10 NF2-related schwannomas and in 4 out of 4 investigated Schwann cell tumors associated with schwannomatosis." (PMID 27236462, 2016). "Of 43 total NF2 patients undergoing resection of nerve sheath tumors, 11 specimens from 11 (26%) patients were found to be benign nerve sheath tumors exhibiting hybrid features of both neurofibroma and schwannoma." (PMID 26709712, 2016). "Thus, the results from both loss- and gain-of-function experiments strongly implicate FAK1 inhibition as the main mechanism through which crizotinib mediates its effects in NF2-null schwannoma cells." (PMID 27363027, 2016). "The most dramatic changes in terms of ErbB2 receptor upregulation and Ras-MAPK pathway activation were found in nerve tissue of P0-Cre;Nefh-Cre;Nf2 fl/+ mice, correlating with the appearance of macroscopic nerve swelling and schwannoma-like structures following nerve injury." (PMID 27236462, 2016). "Our findings indicate that hybrid tumors having dual morphologic and immunophenotypic features of schwannoma/neurofibroma may be more prevalent in the NF2 population than previously realized." (PMID 26709712, 2016). "However, schwannomas from SMARCB1 positive patients follow a four-hit, three-step model of tumorigenesis in which both alleles of SMARCB1 and NF2 genes are inactivated in the tumor." (PMID 25739810, 2015). "NF2 has an incidence of 1 in 33.000 live births, is characterized by the presence of schwannomas, meningiomas and other tumors, and distinctively characterized by the presence of bilateral vestibular schwannomas (VS) with a nearly complete penetrance at the age of 60." (PMID 25739810, 2015). "However, SMARCB1-associated schwannomas follow a four-hit, three-step model, in which both alleles of SMARCB1 and NF2 genes are inactivated in the tumor, with one of the steps being always the loss of a big part of chromosome 22 involving both loci." (PMID 25739810, 2015). "Furthermore, in a recent NF2 genetically engineered mouse model, generated through excision of the NF2 gene driven by Cre expression (restricted to periostin promoter element), the NF2 mice developed multiple schwannomas in peripheral and cranial nerves." (PMID 26104281, 2015). "The NF2 gene is inactivated in most, if not all, schwannomas and is frequently lost in conjunction with the loss of chromosome 22." (PMID 23354516, 2013). "Of 20 schwannoma samples, 16 were informative when analyzed with both NF2 gene markers (80%)." (PMID 22911524, 2012). "Schwannomatosis can be heritable or sporadic, manifests as a propensity to develop schwannomas in the absence of the usual signs of NF2, and can be associated with any nerve in the orbit." (PMID 22937797, 2012). "Schwannomas are a principal feature of two hereditary tumor diseases, NF2 and schwannomatosis." (PMID 22911524, 2012). "Although biallelic NF2 mutations are found in schwannomas, no germ line event is detected in schwannomatosis patients." (PMID 21255467, 2011). "It is now known that between 20–40% of sporadic schwannomas are inactivated by NF2 methylation and in a similar fashion to TP16 this could involve both copies of NF2 and explain why some tumours do not harbour identifiable point mutations or LOH." (PMID 19545378, 2009). "Truncating variants in NF2 cause severe phenotypes with higher tumor burden, early mortality, and a lifetime need for multiple surgeries due to lack of medications that control schwannoma growth." (PMID 42073536, 2026). "Additionally, NF2-EVs promote the proliferation of NF2 schwannoma cells." (PMID 41149489, 2025). "In NF2 patients, this hypomethylation suggests an epigenetic pathway that enhances oncogenic miRNA and gene expression and potentially could contribute to pathogenesis of the schwannomas." (PMID 40843672, 2025).
schwannoma (continued). "Remarkably, 57% of patients clinically diagnosed with non-NF2-related SWN but without germline LZTR1 or SMARCB1 lesions exhibit mosaic NF2-related SWN as determined by identical pathogenic NF2 variants detected in two independent schwannomas." (PMID 40794298, 2025). "Additionally, neurofibromatosis 2 may present with cataracts, retinal abnormalities, and, rarely, cutaneous NF2-related schwannomas under the skin." (PMID 38541874, 2024). "Additionally, surgical removal is not possible in multiple situations where tumors commonly arise in patients with neurofibromatosis 2, and radiation treatment may transform or accelerate the growth of NF2-related schwannomas." (PMID 38541874, 2024). "How heterogeneity develops in NF2-mutant schwannomas is unknown." (PMID 36944680, 2023). "However, the diagnosis of NF2 was based primarily on the occurrence of bilateral schwannomas without genetic testing, with location not a certainty in the diagnostic criteria for NF2." (PMID 37904024, 2023). "These consistent results offer the possibility that CUDC907 will promote schwannoma regression in patients with diverse NF2 mutations and support clinical evaluation of CUDC907 for NF2-associated schwannomas and potentially other cancers driven by NF2 pathogenic variants." (PMID 35875610, 2022). "Interestingly, schwannomatosis-related schwannomas also exhibit NF2 inactivation." (PMID 34604034, 2021). "Histologically, schwannomatosis-associated lesions may also exhibit unusual growth patterns like NF2-associated lesions, including infiltrative intraneural growth, and myxoid changes, though cutaneous “plaque-like” schwannomas are not seen." (PMID 31161239, 2020). "However, some researchers pointed out that the NF2 methylation is not a mechanism of merlin loss in schwannomas." (PMID 32244314, 2020). "Interestingly, on pathologic review, up to 26% of nerve sheath tumors in NF2 exhibit features of both neurofibroma and schwannoma, and most lesions diagnosed as neurofibroma are more appropriately classified as hybrid neurofibroma/schwannomas." (PMID 31161239, 2020). "Furthermore, we show that the metabolic reprogramming of NF2 schwannoma cells is tightly regulated by peroxynitrite, suggesting that novel therapeutic targets for NF2 treatment could be identified among oxidized proteins." (PMID 31171721, 2019). "Moreover, recent evidence suggests that the nerve microenvironment and an unresolved inflammatory response could play an important role in the development of NF2 schwannomas." (PMID 31171721, 2019). "Until now, the metabolic profile of human NF2 schwannoma cells had been largely unknown." (PMID 31171721, 2019). "However, the analysis of a schwannoma from each of these patients indicated a somatic NF2 gene mutation which is not unusual, since somatic NF2 mutations are frequently observed in schwannomas." (PMID 27921248, 2017). "Indeed, hypermethylation of the NF2 promoter region has been shown to be frequent in schwannomas and could, therefore, represent an alternative mechanism of NF2 inactivation." (PMID 27921248, 2017). "NF2 mutations are detected in schwannomas irrespective of whether they occur sporadically or in the context of schwannomatosis or NF2." (PMID 27921248, 2017). "However, patient-mimicking schwannomas could only be provoked in animals with combined heterozygous nf2 knockout in Schwann cells and axons." (PMID 27236462, 2016). "This in turn coincides with substantial cellular proliferation resulting in tumorlet formation, identical to NF2-related schwannomas again underlining the notion that tumors do not diversify solely in terms of genetic alterations, but also with respect to the nature of their microenvironment." (PMID 27236462, 2016). "In addition, PAK1 activity is upregulated in NF2 patient-derived schwannomas." (PMID 26219339, 2015).
schwannoma (continued). "While several mitogenic pathways are known to be upregulated in NF2-mutant cells, despite considerable effort, there is as yet no consensus as to how loss of the NF2 tumor suppressor gene leads to schwannoma growth, nor are there effective medical therapies for this disorder." (PMID 21072183, 2010). "During NF2-SWN progression, schwannoma cells migrate from the extracellular matrix (ECM)-rich internal auditory canal to the arachnoid-lined brainstem, yet mechanisms driving this transition remain incompletely defined." (PMID 41756440, 2026). "Nerve sheath tumors such as NF and Schwannoma are common, with the disease prevalence being 1:3500 for NF1 and 1:50,000 for NF2." (PMID 39857711, 2025). "Single-cell RNA sequencing (scRNA-seq) of 22 schwannomas including sporadic tumours and those from patients with NF2-related SWN and non-NF2-related SWN indicated intra- and inter-tumoral transcriptional heterogeneity of schwannomas." (PMID 40794298, 2025). "In patients with non-NF2-related SWN, schwannomas of the peripheral nerves have been observed in 81–89% of patients whereas spinal schwannomas have been noted in 74% of these patients." (PMID 40794298, 2025). "About one third of patients with non-NF2-related SWN develop segmental schwannomatosis, with schwannomas apparently confined to a body segment such as a limb or several spinal nerve roots." (PMID 40794298, 2025). "Instead, tumorigenesis of schwannomas in patients with SMARCB1‐ (and LZTR1-) related SWN appears to follow a four‐hit/three‐step model that includes somatic biallelic inactivation of the NF2 gene." (PMID 40794298, 2025). "Murine Nf2-mutant schwannoma cells also exhibited striking Nrg1−stimulated ruffling and EIPA-sensitive dextran-488 uptake that was reversed by Nf2 re-expression or ezrin depletion." (PMID 36944680, 2023). "Her NF2 history is positive for a right optic nerve sheath meningioma, CNIII schwannoma requiring radiation therapy and post gross total resection of right frontotemporal anaplastic meningioma followed by radiation." (PMID 36975468, 2023). "In the central para-sellar skull base, CN V schwannomas predominate, while CN III, IV, and VI schwannomas are rare, except in the setting of NF2-related schwannomatosis." (PMID 37489465, 2023). "Schwannoma is a primary BTCNS that occurs sporadically or as part of a genetic syndrome (Neurofibromatosis type 2-related schwannomatosis, NF2)." (PMID 37629179, 2023). "In such patients, the identification of a somatic non-NF2 driver alteration such as this newly described YAP1 fusion, can help ascertain the diagnosis of a sporadic schwannoma." (PMID 35986430, 2022). "Due to the benign tumor entity and the homogenous ultrasound characteristics of neurofibromas and schwannomas, the disease NF1 can be regarded as a model to explore the potential of SWE for NF2 and PNTs." (PMID 35204451, 2022). "Though it was initially suspected that malignant peripheral nerve sheath tumors (MPNST) may be more common in NF2 patients, a study of a large cohort of NF2 patients showed no convincing evidence for an increased risk of malignant transformation of schwannomas in non-irradiated patients." (PMID 31161239, 2020). "There has been comparatively less research into the role of TAMs in NF2-related VS, but small histopathological studies have demonstrated Iba1 and CD68-positive macrophage occurrence among human schwannoma samples." (PMID 32642684, 2020). "By contrast, schwannomas from LZTR1-unrelated schwannomatosis patients, as well as patients with NF2, showed diffuse but positive LZTR1 immunostaining." (PMID 27921248, 2017). "Human primary VS cells, HEI-193 schwannoma cells, and SC4 Nf2−/− Schwann cells were used to investigate the inhibitory effects of SFN in vitro." (PMID 27805058, 2016). "The four-hit, three-step model, is also present in schwannomas from LZTR1 patients, involving LZTR1 and NF2 genes." (PMID 25739810, 2015).
schwannoma (continued). "Schwannomas of LZTR1 positive patients also follow a three-step four hit model involving LZTR1 and NF2 genes." (PMID 25739810, 2015). "In addition to vestibular schwannomas and schwannomas occurring within the spinal cord and along peripheral nerves, mutations in the NF2 gene are responsible for virtually all non-hereditary, sporadically occurring schwannomas and 50% of sporadic meningioma cases." (PMID 25012216, 2014). "In the patients with NF2 and SWN in this study, there was great variability in the ADC values of the peripheral schwannomas, presumably due to the differences in cellularity and relative proportion of Antoni A and Antoni B patterns within each schwannoma." (PMID 24967287, 2013). "For patients with unilateral VS and other non-intradermal schwannomas, LZTR1 variants must ideally be ruled out before confirming a diagnosis of NF2-SWN." (PMID 41160189, 2025). "In a proportion of schwannomatosis patients without identifiable germline LZTR1 or SMARCB1 PV, somatic 22q LOH has been detected in schwannomas with or without an identifiable somatic NF2 PV." (PMID 40794298, 2025). "Likewise, schwannomas of patients with SMARCB1- and LZTR1-related SWN exhibit biallelic NF2 gene inactivation as mentioned in the previous section." (PMID 40794298, 2025). "In a comprehensive analysis, the methylation profiles were assessed in a cohort of 44 schwannoma tumour samples, comprising 37 schwannoma tumour samples, 29 from individuals without NF2 and 8 from patients diagnosed with NF2." (PMID 40843672, 2025). "Isolated schwannomas in patients with SMARCB1-, LZTR1- or NF2-related SWN may already be present in early childhood or in young adults." (PMID 40794298, 2025). "SWN has a phenotypic overlap with NF2, characterized by the presence of schwannomas, but without VS development and with distinct underlying genetics, including mutations identified in SMARCB1 and LZTR1." (PMID 38353122, 2024). "In patients with NF2, the abundance of Foxp3-positive regulatory T cells in progressing schwannomas significantly exceeded that in non-progressing cases, indicating a potential link between the presence of these cells and tumor growth." (PMID 38817895, 2024). "Heterozygous/hemizygous knockouts of Nf2 are cancer prone and demonstrate a tumor spectrum that differs significantly from that observed in NF-2 patients; they do not develop Schwannomas, a prominent feature of NF-2." (PMID 39415595, 2024). "This is in cases where patients presenting with bilateral schwannomas have no affected parent or family history of NF2 and do not return a positive genetic test." (PMID 37904024, 2023). "A comparison of RNA sequencing profiles revealed differential and higher expression of FGF7 in painful versus non-painful schwannomas among NF2 patients, thus identifying a potential mediator of pain." (PMID 37048724, 2023). "Although NF2 and SMARCB1 mutations have been reported in schwannomas from other anatomical sites, we did not observe these aberrations." (PMID 37535242, 2023). "In summary, we demonstrated that CUDC907 reduced the activity of three major signaling pathways in NF2 schwannomas (HDAC, PI3K, and YAP) and consistently reduced viability and induced apoptosis in several schwannoma cell models and in all five genetically unique primary VS studied." (PMID 35875610, 2022). "Biallelic inactivation of NF2 represents the primary or sole oncogenic driver event in the vast majority of schwannomas; in addition, SH3PXD2A-HTRA1 fusions have been recently identified as an alternative oncogenic driver in a subset of sporadic schwannomas." (PMID 35986430, 2022). "The results of phenotypic and molecular studies obtained using human schwannoma model cells, VS primary cells, and an orthotopic allograft model are in good agreement, providing strong evidence that CUDC907 is a remarkable drug candidate for NF2." (PMID 35875610, 2022).